RETN (resistin)
Diseases named in the same sentence as RETN in open-access papers (continued):
Sharing a sentence is not in itself a finding about the gene and the disease.
breast cancer (continued). "In addition, those with the G allele of the RETN rs3219175 polymorphism were more likely than those with the A allele to develop breast cancer (AOR: 1.295; 95% CI: 1.065-1.575; p<0.05)." (PMID 32226495, 2020). "Leptin and resistin are well-known adipokines linked to breast cancer." (PMID 32257945, 2020). "This study sought to determine whether certain polymorphisms in the gene encoding resistin, RETN, increase the risk of breast cancer susceptibility." (PMID 32226495, 2020). "The TNF-α c.-308G>A (rs1800629) polymorphism was found to be associated with breast cancer risk in a study conducted in Mexico, and another Mexican study found associations between the RETN c.-225C>G (rs1862513) and CAP1 c.881G>A (rs35749351) polymorphisms and breast cancer risk." (PMID 30781715, 2019). "High levels of resistin in both serum and plasma have been linked to risk of breast cancer." (PMID 27314854, 2016). "In addition, it was recently suggested that circulating leptin, resistin, and visfatin levels have some diagnostic values for breast cancer in postmenopausal women." (PMID 27293305, 2016). "Both elevated leptin and resistin concentrations was associated with the promotion of cancer stem cell survival and the promotion of invasion and migration via epithelial to mesenchymal transition in breast cancer cells, which contributes to the development of treatment resistance." (PMID 32257945, 2020). "More data are needed to determine if resistin could serve as a diagnostic breast cancer biomarker." (PMID 27314854, 2016). "For instance, resistin enhances the growth and aggressiveness of breast cancer cells by activating the STAT3 pathway." (PMID 40002704, 2025). "The knowledge obtained from this research would help to better understand the signaling mechanisms behind how resistin promotes inflammation in breast cancer cells." (PMID 38252319, 2024). "Previous studies have shown that adipokines such as adiponectin can induce cell apoptosis and enhance the effects of DOX in breast cancer while leptin and resistin can decrease cancer cell apoptosis and reduce the efficacy of DOX." (PMID 38238320, 2024). "Resistin-mediated EVs secretion can be supported by the fact that, in MDA-MB-231 invasive mammary cancer cells, resistin promotes an increase in intracellular calcium concentration, a phenomenon known to induce EV secretion." (PMID 38137922, 2023). "A novel adipokine, resistin, is highly stimulated in patients with breast cancer and facilitates cell proliferation, metastasis, and breast cancer cell migration." (PMID 37213283, 2023). "Evaluation of the cytokine profiles of Black and white women with breast cancer uncovered a higher expression of Resistin and IL6 in the serum samples of Black women." (PMID 36702853, 2023). "TLR4, as a receptor of resistin, which has high expression in human breast cancer, also mediates the promoting effect of resistin on epithelial-to-mesenchymal transition and stemness in breast cancer, combined with the downstream NF-κB/STAT3 pathway." (PMID 37576399, 2023). "It was demonstrated that CAAs surrounding breast cancer are smaller and exhibit lower lipid content, reduced levels of adipocyte markers (leptin, adiponectin, resistin, FABP4), and overexpression of proinflammatory cytokines and matrix-remodeling proteins." (PMID 37481560, 2023). "There is evidence that resistin increases aggressiveness in breast cancer, favoring processes such as tumor growth by increasing BCL-2 and BCL-xL activity, accompanied by a decrease in cleaved caspase-7 and -3." (PMID 38137922, 2023). "For example, adipokines such as LEP and RETN promote metastasis through activation of ezrin, radixin and moesin proteins in breast cancer cells." (PMID 36362348, 2022). "In this study, we examined the impact of resistin on ADSCs in promoting breast cancer cell malignancy, with an emphasis on their interaction with breast cancer cells in the context of the tumor microenvironment." (PMID 36104403, 2022).
breast cancer (continued). "Clinical data from independent groups link resistin expression in breast cancer tissue with adverse clinical and pathological characteristics as well as decreased survival." (PMID 36077676, 2022). "The concentration of resistin applied to ADSCs in this study was in a range covering human resistin levels detected in the serum of breast cancer patients." (PMID 36104403, 2022). "For breast cancer, resistin is involved in epithelial-mesenchymal transition and stemness, which are critical to metastasis and tumorigenesis via NF-κB/STAT3 pathways." (PMID 35073877, 2022). "In breast cancer, resistin induced the phosphorylation of c-Src, PP2A, PKCα, ezrin, radixin and moesin, and increased vimentin expression, promoting cell invasion and metastasis." (PMID 36291097, 2022). "More recent research has proposed that some adipocytokines, such as visfatin and resistin, promote breast cancer progression through cell–cell interactions within the breast tumor microenvironment." (PMID 36104403, 2022). "In a comprehensive differential survival analysis from the Cancer Genome Atlas (TCGA), resistin was elevated more than four times in breast cancers from African American patients." (PMID 36077676, 2022). "They suggested that the adipocyte-related TAZ/resistin signal was conducive to the development of breast cancer tumors, and the resistin neutralization represented a promising therapeutic strategy." (PMID 35701840, 2022). "Knockdown of the adipocytic TAZ in mice downregulated the secretion of resistin and inhibited breast cancer proliferation and stemness." (PMID 36077676, 2022). "Recently, it has been described that high resistin expression in breast cancer cells confers resistance to chemotherapy through suspension of doxorubicin-induced apoptosis." (PMID 36077676, 2022). "A previous study has been demonstrated that resistin was highly expressed in serum and tumor tissue samples of patients with breast cancer." (PMID 33517609, 2021). "High expression and increased serum level of harmful pro-inflammatory cytokines including resistin, TNF-α, IL-6, and IL-8 are associated with shorter survival and poor prognosis of breast cancer." (PMID 33517609, 2021). "Gündoğdu used KNN and SVM algorithms with 5 features (age, BMI, glucose, resistin, and adiponectin) as inputs for the prediction of breast cancer." (PMID 34730888, 2021). "Serum resistin levels in breast cancer patients were positively correlated with tumor size, malignancy and lymph node metastasis and decreased disease-free and overall survival rates were observed in the high resistin expressing patients." (PMID 34485124, 2021). "In this study, the results obtained by M5 with 5 features (age, BMI, glucose, resistin, and adiponectin) showed that pattern recognition networks can be effectively used for breast cancer prediction." (PMID 34730888, 2021). "In MDA-MB-231 TNBC cell lines, resistin enhances invasion and migration of the breast cancer cells, thereby promoting metastasis." (PMID 34944905, 2021). "Earlier, we reported that the levels of resistin and IL-6 were significantly more elevated in the serum of African American women with breast cancer than in their Caucasian American counterparts." (PMID 34572725, 2021). "The mRNA expression of resistin (3.5-fold) and IL-6 (15-fold) in PBMCs of breast cancer patients significantly increased in comparison to healthy controls." (PMID 33517609, 2021). "The higher expression levels of resistin and visfatin are reported in a number of malignancies such as colorectal, lung, gastroesophageal, endometrial and breast cancer." (PMID 34588926, 2021). "We found that resistin treatment led to the reduced expression of Let-7 family miRNAs in breast cancer (BC) cells, with the highest downregulation reported for Let-7a." (PMID 34572725, 2021). "Our findings further implicate the TAZ/Resistin network as potential chemotherapeutic targets for breast cancer treatment." (PMID 33318171, 2020).
breast cancer (continued). "An earlier study stated that the mean serum resistin was significantly higher in breast cancer cases than in controls and patients with benign breast lesions." (PMID 33247685, 2020). "Adipocytic Resistin knockdown attenuated Adipo-CM–induced breast cancer intracellular signaling activation, which is similar to adipocytic TAZ knockdown." (PMID 33318171, 2020). "The cytokine resistin participates in several physiological and pathological processes, including metabolism, inflammation, autoimmunity, and various cancers, including breast cancer." (PMID 33313320, 2020). "We analyzed levels of resistin expression in breast cancer tissue and samples from The Cancer Genome Atlas database." (PMID 32226495, 2020). "Here, we show a role of TAZ in mature adipocytes regulating Resistin expression and secretion, which in turn promotes breast cancer cell proliferation and maintenance of stemness." (PMID 33318171, 2020). "IL-6 regulates insulin, resistin and estrogen, and thereby directly affects breast cancer development." (PMID 32824813, 2020). "Rates of positive and strongly positive resistin expression were significantly higher in breast cancer tissue than in normal breast tissue (P < 0.001 and P = 0.001, respectively)." (PMID 33313320, 2020). "Our mechanistic studies showed that diet-induced adiposity prompted adipocytic TAZ/Resistin expression and therefore enhanced breast cancer cell proliferation and stemness maintenance." (PMID 33318171, 2020). "Mechanistically, adipocytic TAZ activates breast cancer intracellular signaling pathways through Resistin secretion; we next sought to explore the role of Resistin on this signaling." (PMID 33318171, 2020). "Stimulation of breast cancer cells with resistin not only enhances their growth and stemness but also results in chemoresistance through STAT3 activation." (PMID 33123472, 2020). "Another study also showed that serum resistin was elevated in breast cancer compared with healthy controls and benign breast lesions pointing to its importance as a diagnostic biomarker." (PMID 33247685, 2020). "We detail the clinical prognostic significance of a positive association between resistin and EGFR expression in breast cancer." (PMID 33313320, 2020). "Our findings contribute to data concerning the correlation between resistin and breast cancer development." (PMID 32226495, 2020). "AA and CA breast cancer patients have resistin and IL-6 as the most differentially-expressed cytokines, with a relatively higher level of expression in AA patients." (PMID 32824813, 2020). "The rate of positive resistin expression in breast cancer tissue specimens was 83.2% (326/392), which included 82 (20.9%) strongly positive cases; corresponding rates in normal breast tissue specimens were 23.8% (10/42) and 0.0% (0/42), respectively." (PMID 33313320, 2020). "Based on the ROC curve, serum resistin cutoff value ≥ 737.6 ng/L can be used as a cutoff point at which 83.3% of breast cancer patients (T1 and T2 stages) can be early diagnosed correctly, but 2.5% of normal subjects are false positive." (PMID 33247685, 2020). "Elevated levels of CEACAM1, resistin and visfatin were observed in breast cancer patients when compared with normal control and benign groups." (PMID 33247685, 2020). "This study details risk associations between resistin and RETN SNPs in breast cancer susceptibility in Chinese Han women." (PMID 32226495, 2020). "CEACAM1, resistin and visfatin are valuable in early diagnosis of breast cancer, with visfatin being preferentially used in staging." (PMID 33247685, 2020). "As shown in the present study, serum level of resistin in different stages of breast cancer patients was significantly higher when compared with the benign and control groups." (PMID 33247685, 2020).
breast cancer (continued). "Here, our study establishes the FFA/PPARγ/TAZ/Resistin axis as an essential signaling pathway in adipocytes that facilitates breast cancer proliferation and stemness, with an implication of a diagnostic and therapeutic avenue for breast cancer." (PMID 33318171, 2020). "In view of that, this study was designed to evaluate the serum levels of CEACAM1, resistin, visfatin in order to explore their significance in the early diagnosis and staging of Egyptian breast cancer patients." (PMID 33247685, 2020). "High concentrations of leptin and resistin favor cancer cell proliferation and have recently been reported to be casual factors in acquired breast cancer treatment resistance." (PMID 32257945, 2020). "Significant correlations have been observed between high resistin expression in breast cancer tissue and tumor stage, tumor size, lymph node metastasis, estrogen receptor (ER) status, and poor survival." (PMID 33313320, 2020). "In the present study, a higher serum resistin concentration was observed in the group of female dogs with mammary carcinoma (CBMT) when compared to the group of healthy dogs." (PMID 32903534, 2020). "PP2A activity is also decreased by resistin, an adipocyte-secreted factor known to be elevated in breast cancer patients." (PMID 31382374, 2019). "Few Latin American studies tested the association between genes in inflammation and energy balance pathways and breast cancer risk (TNF-α, RETN, CAP1, and PTGS2 genes)." (PMID 30781715, 2019). "•We established optimal conditions for resistin treatment in human breast cancer cells in vitro as initial necessary step for performing further experiments." (PMID 31417946, 2019). "Here, we provide data on the effect of resistin on epithelial to mesenchymal transition (EMT) in breast cancer cells in vitro." (PMID 31417946, 2019). "This is the very first report for such effect of resistin in ovarian cancer cells, even though resistin was earlier reported to increase invasion, and the mesenchymal marker vimentin in breast cancer cells." (PMID 30131543, 2018). "It was recently reported that certain resistin (RETN) and CAP1 gene variants were associated with increased risk of breast cancer among Mexican women." (PMID 30524378, 2018). "Although over twenty adipokines are known; only twelve (adiponectin, leptin, IL-6, TNF-α, HGF, PAI–1, resistin, secreted frizzled-related protein 5 (SFRP-5), lipocalin 2, IL-8, apelin and visfatin) have been implicated in breast cancer." (PMID 29088874, 2017). "To assess the effect of c-Src on resistin-induced invasion, we pre-treated breast cancer cells with the c-Src inhibitor PP2, and analyzed the invasion ability of MDA-MB-231 cells via a transwell assay." (PMID 26729407, 2016). "To investigate the role of PP2A on cancer metastasis, we measured invasion activity of MDA-MD-231 cells pretreated with okadaic acid, and found that inhibition of PP2A increased the resistin-induced breast cancer cells invasion." (PMID 26729407, 2016). "The resistin gene had expression levels almost 5-fold greater in AA breast cancer tumors than in CA women." (PMID 27314854, 2016). "Previous studies indicated that resistin expression is higher in serum and tissue of AA breast cancer patients compared to Caucasian American (CA) patients." (PMID 27314854, 2016). "Prior studies that found elevated resistin in postmenopausal women were comparing postmenopausal breast cancer patients with healthy postmenopausal patients." (PMID 27314854, 2016). "In conclusion, we confirmed higher resistin expression in AA women and discovered that resistin is associated with ER-, PR-, HER2-negative and triple negative subtypes, which are more aggressive breast cancer subtypes with limited treatment options." (PMID 27314854, 2016). "Here, we report that resistin stimulated invasion and migration of breast cancer cells as well as phosphorylation of c-Src." (PMID 26729407, 2016).
breast cancer (continued). "To confirm the metastatic effect of resistin on the breast cancer cells, we tested another breast cancer MCF-7 cells." (PMID 26729407, 2016). "Either inhibition of c-Src and PKCα or knock-down of ezrin blocked resistin-induced breast cancer cells invasion." (PMID 26729407, 2016). "Previous studies examining the role of resistin in menopause status of breast cancer patients have been unclear." (PMID 27314854, 2016). "In comparisons of molecular subtypes, resistin levels were significant higher in triple negative than in luminal A breast cancer." (PMID 27314854, 2016). "This work investigates differential resistin gene expression in human breast cancer tissues of specific stages, receptor subtypes, and menopause statuses in AA and CA women." (PMID 27314854, 2016). "In all these evaluations, we compared AA to CA cases to better understand the role of resistin in breast cancer and health disparities, using the whole-population expression data to clarify if differences were stage- and subtype-specific or race-specific." (PMID 27314854, 2016). "Our results identified that there were statically higher serum levels of leptin, visfatin, and resistin and lower serum level of adiponectin in breast cancer patients compared to healthy controls." (PMID 25838618, 2015). "Expression of resistin in breast cancer tissue has been considered as a marker of prognosis and hormone therapy stratification; and resistin has also been demonstrated to induce adhesion of hepatocellular carcinoma cells to the endothelium." (PMID 25404641, 2015). "As well as higher levels of serum resistin detected in the inflammatory component of several cancer sub-types, such as gastroesophageal, colorectal, endometrial and breast cancers." (PMID 26097512, 2015). "We next performed a time-course study by treating the breast cancer cells with rh-resistin for various time intervals." (PMID 25868978, 2015). "Numerous studies have reported elevated levels of resistin in certain forms of cancer, such as gastroesophageal, gastric, colorectal, endometrial and postmenopausal breast cancer." (PMID 26097512, 2015). "This work helps elucidate molecular mechanisms of breast cancer health disparity and identifies putative biomarkers and therapeutic targets such as resistin, and the aurora B and polo-like kinase signaling pathways for treating AA breast cancer patients." (PMID 24324792, 2013). "Several genes have increased expression in AA tumors, including a few with direct ties to breast cancer such as resistin (RETN)." (PMID 24324792, 2013). "In the future, clarifying the mechanism of increased resistin in breast cancer will be necessary." (PMID 40584290, 2025). "By reducing the inflammatory milieu in the breast epithelium, targeting resistin inhibition may be a sound therapeutic strategy to go beyond the resistance of the commonly used therapy methods for breast cancer." (PMID 40584290, 2025). "TLR4 functions as a receptor for resistin, an adipokine related to obesity and T2DM which has been implicated in tumorigenesis through PI3K-AKT and MAPK pathways and is suspected to confer resistance to chemotherapy in breast cancer cells." (PMID 37626871, 2023). "Interestingly, resistin promotes breast cancer metastasis by increasing Src activity and phosphorylation and favoring PKCα translocation to the nucleus." (PMID 38137922, 2023). "These clinical data and our preclinical findings together suggest the potential of CXCL5 secretion induced by resistin-stimulated ADSCs in the breast tumor microenvironment, and that promoted breast cancer cell malignancy with the participation of ERK signaling pathway." (PMID 36104403, 2022). "The results showed that application of PD98059 largely reduced the migration ability of MDA-MB-231 cells after co-culture with R-ADSCs compared with the group without PD98059 treatment, suggesting the participation of ERK pathway in breast cancer cell malignancy induced by resistin-stimulated ADSCs." (PMID 36104403, 2022).